CLN8 (CLN8 transmembrane ER and ERGIC protein)
Description:
Could play a role in cell proliferation during neuronal differentiation and in protection against cell death.
Synonyms: C8orf61; FLJ39417; TLCD6; EPMR
Tractability: Antibody: UniProt predicts a signal peptide or a membrane-spanning region.
Gene: Protein-coding gene on chromosome 8 (1,755,778 to 1,801,711, forward strand). Ensembl gene ENSG00000182372.
Subcellular location: Endoplasmic reticulum membrane; Endoplasmic reticulum-Golgi intermediate compartment membrane; Endoplasmic reticulum
Gene Ontology:
Molecular function: ceramide binding; protein binding
Biological process: ceramide metabolic process; cholesterol metabolic process; nervous system development; phospholipid metabolic process; ceramide biosynthetic process; lipid biosynthetic process; lipid homeostasis; lipid transport; negative regulation of proteolysis; protein catabolic process
Cellular component: endoplasmic reticulum; endoplasmic reticulum-Golgi intermediate compartment; membrane; endoplasmic reticulum membrane; endoplasmic reticulum-Golgi intermediate compartment membrane
Genetic constraint (gnomAD): Loss-of-function variants: 20 observed, 24.57 expected, observed/expected ratio (o/e) 0.81, 90% interval 0.57 to 1.18. The upper end of that interval is the gene's LOEUF score, 1.18, which puts it in group 5 of 6, group 1 being the genes least tolerant of losing a copy. Missense variants: 415 observed, 383 expected, observed/expected ratio (o/e) 1.08, 90% interval 1 to 1.17. Synonymous variants: 188 observed, 159.93 expected, observed/expected ratio (o/e) 1.18, 90% interval 1.04 to 1.33.
Gene-disease validity (ClinGen):
ClinGen rates the evidence that CLN8 causes each of these diseases.
neuronal ceroid lipofuscinosis (autosomal recessive): Definitive.
Homologues: Orthologues: chimpanzee CLN8 (99% identical), macaque CLN8 (97% identical), dog CLN8 (89% identical), rabbit CLN8 (89% identical), guinea pig CLN8 (87% identical), rat Cln8 (87% identical), mouse Cln8 (86% identical), pig CLN8 (76% identical), tropical clawed frog cln8 (58% identical), zebrafish cln8 (56% identical). Paralogues in human: TLCD3B (20% identical), TLCD2 (17% identical), TLCD3A (16% identical), TLCD1 (14% identical), TLCD4 (13% identical).
Diseases named in the same sentence as CLN8 in open-access papers:
CLN8 is named in the same sentence as 41 diseases in open-access papers, as found by Europe PMC text mining. Sharing a sentence is not in itself a finding about the gene and the disease. The quoted sentences say what the papers report.
epilepsy (19 papers, 2005 to 2025). A brain disorder characterized by episodes of abnormally increased neuronal discharge resulting in transient episodes of sensory or motor neurological dysfunction, or psychic dysfunction. "While the variant causing Northern epilepsy has only been found in the Finnish population, other pathogenic variants in CLN8 have been found elsewhere with different NCL disease phenotypes (OMIM 600143)." (PMID 34831381, 2021). "Pathogenic variants in CLN8 have been associated with Northern epilepsy and neurodegenerative diseases typified by lipopigment accumulation." (PMID 34816733, 2021). "Our recent whole-exome sequencing (WES) study in two families with affected siblings and a follow-up study identified ceroid-lipofuscinosis, neuronal 8 (epilepsy, progressive with mental retardation) (CLN8) as a potential genetic risk factor for ASD." (PMID 26657971, 2015). "Mutations in CLN8 result in two distinct NCL phenotypes in humans: Northern epilepsy (Progressive epilepsy with mental retardation, EPMR, OMIM 600143) described in Finnish patients, and variant late infantile onset NCL in a subset of Turkish patients." (PMID 15826318, 2005). "The human phenotype is characterized by epilepsy, progressive psychomotor deterioration and visual loss, while motor neuron degeneration (mnd) mice with a Cln8 mutation show progressive motor neuron dysfunction and retinal degeneration." (PMID 15826318, 2005). "We analyzed the expression of the Cln8 gene during mouse development and in the hippocampal kindling model of epilepsy to gain understanding of the role of CLN8 in the disease mechanisms underlying both human and mouse NCLs." (PMID 15826318, 2005). "Mutations in CLN8 have been reported to cause epilepsy and neurodegeneration." (PMID 40894639, 2025). "Considering the clinical features of epilepsy, cerebellar and optic nerve atrophy, macular dystrophy, developmental delay and progressive deterioration together with a CLN8 mutation and relevant ultrastructural pathology, the diagnosis of neuronal ceroid lipofuscinosis type 8 was made." (PMID 34201538, 2021). "Northern epilepsy is caused by a missense variant (c.70C > G) in the CLN8 gene encoding the CLN8 transmembrane ER and ERGIC protein, which is involved in the transport of newly synthesized lysosomal enzymes from the endoplasmic reticulum (ER) to the Golgi apparatus." (PMID 34831381, 2021). "A novel mutation in CLN8 may cause Northern Epilepsy cases in Turkey." (PMID 37489460, 2023). "In a mouse model of kindling epilepsy (electrical shock induced epilepsy), the expression of cln8 was up-regulated in hippocampus." (PMID 41339323, 2025). "Evaluating the epilepsy and CMAR panels revealed 5 P/LP variants in genes that generally associate with homozygous recessive inheritance (QARS, CLN8, PPT1, CSTB, and FKRP) in heterozygous decedents, indicating that these are likely incidental findings." (PMID 38229148, 2024). "We report a novel CLN8 mutation as a cause for NCL8 in a girl with developmental delay and epilepsy, cerebellar syndrome, visual loss, and progressive cognitive and motor regression." (PMID 34201538, 2021). "ARHGEF10, together with CLN8, also falls within the 123 kb deletion of patient 6 who has motor coordination problems and epilepsy." (PMID 33925474, 2021). "Of note, a terminal deletion at 8p23.2-pter, including CLN8, was identified in a Han Chinese boy with autism, epilepsy and severe intellectual disability." (PMID 25806950, 2015). "Expression of Cln8 mRNA in the central nervous system (CNS) was also analyzed in the hippocampal electrical kindling model of epilepsy, in which Cln8 expression was rapidly up-regulated in hippocampal pyramidal and granular neurons." (PMID 15826318, 2005). "In the kindling model of experimental epilepsy a rapid up-regulation of Cln8 expression was detected in the brain, especially in hippocampal regions CA3 and the granular cell layer of the dentate gyrus." (PMID 15826318, 2005).
epilepsy (continued). "Also, ceroid lipofuscinosis (neuronal 8, Northern epilepsy variant, OMIM #610003) is caused by biallelic variants of CLN8." (PMID 37895270, 2023). "Notably, CLN8 and DLGAP2 are associated with autism, epilepsy and intellectual disabilities." (PMID 40790240, 2025). "In all our cases these genes entered the region of deletion, but only Case 1 had seizures, which prevents us from coming to a conclusion of the main contribution of the CLN8 and/or MCPH1 genes in the formation of epilepsy." (PMID 35327368, 2022). "While CLN8 is not a good candidate gene for the phenotype of the idiopathic epilepsy seen in the Belgian breeds, it does underscore the generalizability of the human and canine gene discovery as it relates to epilepsy." (PMID 20441595, 2010).
neuronal ceroid lipofuscinosis (11 papers, 2005 to 2024). "The Late-Infantile-Onset Neuronal Ceroid Lipofuscinosis (LINCL) was related to homozygous mutation of CLN8 gene." (PMID 34238319, 2021). "We report a novel CLN8 mutation causing a variant late-infantile neuronal ceroid lipofuscinosis in the index patient." (PMID 34201538, 2021). "For instance, one of the causative genes for neuronal ceroid lipofuscinosis (NCL, Batten disease), CLN8, encodes for a protein regulating the lysosomal biogenesis; therefore, its deficiency leads to depletion of multiple lysosomal enzymes." (PMID 32106459, 2020). "For instance, it is reported that hERG28 interacts with CLN8, an ER-resident membrane protein involved in neuronal ceroid lipofuscinosis." (PMID 28168949, 2017).
Batten disease (4 papers, 2015 to 2025). "S1A) because mutations in CLN8 gene cause Batten disease, a fatal neurodegenerative lysosomal storage disorder occurring in children." (PMID 39970228, 2025). "Mutations in CLN8 results in characteristic Batten disease symptoms and brain-wide pathology including accumulation of lysosomal storage material, gliosis, and neurodegeneration." (PMID 36369162, 2022). "Notably, mutations in conserved histidine and arginine residues have been frequently observed in CLN8 in patients with Batten disease (H139Y, R204C, and R204L mutations)." (PMID 39970228, 2025). "In addition, efficacy with AAV9 has also been demonstrated in multiple Batten diseases, including CLN3, CLN6, and CLN8, using other routes of administration." (PMID 35025759, 2022). "Recent investigations of other subforms of Batten disease (CLN1, CLN3, CLN6) have emphasized the influence of biological sex on disease and treatment outcomes; however, little is known about sex differences in the CLN8 subtype." (PMID 36369162, 2022).
late infantile NCL (4 papers, 2015 to 2025). "Mutations in CLN8 cause late-infantile neuronal ceroid lipofuscinosis (LINCL)." (PMID 34201538, 2021). "Biallelic mutations in the CLN7 gene cause the variant late infantile NCL (BD) as do biallelic mutations in CLN5, CLN6 and CLN8 genes." (PMID 41173878, 2025). "Studies have suggested variants of Late-Infantile NCLs (LINCLs) include the major type CLN2 and minor types CLN5, CLN6, CLN7, and CLN8." (PMID 31105743, 2019).
autism (3 papers, 2015 to 2025). Persistent deficits in social interaction and communication and interaction as well as a markedly restricted repertoire of activity and interest as well as repetitive patterns of behavior. "In the Niigata sample, heterozygous CLN8 R24H was identified in a male patient with autistic disorder and selective mutism and in a male control." (PMID 25806950, 2015).
developmental delay (3 papers, 2021 to 2025). "This segment contains the OMIM genes DLGAP2, CLN8, and ARHGEF10, which are considered candidate genes for developmental delay, intellectual disability and neurobehavioral disorders." (PMID 40790240, 2025).
Gaucher disease (3 papers, 2019 to 2023). Gaucher disease (GD) is a lysosomal storage disorder encompassing three main forms (types 1, 2 and 3), a fetal form and a variant with cardiac involvement (Gaucher disease - ophthalmoplegia - cardiovascular calcification or Gaucher-like disease). "We found an interesting candidate, an intronic repeat in the CLN8 gene: a SNP within this repeat (rs11986414) and a near-by SNP (rs4875960) are reported to be associated with severity of Gaucher syndrome." (PMID 33413375, 2021). "Of note, a report suggested CLN8 as a genetic modifier after the stimulation of CLN8-mRNA expression in a chemically induced Gaucher disease model." (PMID 30651094, 2019).
Intellectual disability (3 papers, 2015 to 2025). "The DLGAP2 gene is considered by many authors as a gene responsible for the development of progressive intellectual disability, and CLN8 is thought responsible for intellectual disability and seizures." (PMID 35327368, 2022).
Motor neuron degeneration (2 papers, 2005 to 2021). "Motor neuron degeneration (mnd) in mice, caused by spontaneous mutation in Cln8, is the most characterized murine model for CLN8 deficiency." (PMID 34831381, 2021).
progressive epilepsy with mental retardation (2 papers, 2008 to 2015). "Northern epilepsy, also known as progressive epilepsy with mental retardation (EPMR), is caused by a Finnish founder mutation in the CLN8 gene." (PMID 19440452, 2008).
acute pancreatitis (1 paper, 2026). An acute inflammatory process that leads to necrosis of the pancreatic parenchyma. "Loss of CLN8 mitigated the early phase of acute pancreatitis but did not prevent it completely." (PMID 42295516, 2026).
Anxiety (1 paper, 2025). Intense feelings of nervousness, tension, or panic often arise in response to interpersonal stresses. "The Novel Tank Test results indicated that, prior to trehalose treatment, cln8−/− mutant fish exhibited significantly higher swimming activity compared to WT fish, suggesting elevated anxiety-like behaviors in response to a novel environment." (PMID 39791756, 2025). "Using a cln8−/− zebrafish model, we identified significant impairments in locomotion, anxiety, and aggression, along with subtle deficits in social interactions, positioning zebrafish as a useful model for therapeutic studies in NCL." (PMID 39791756, 2025).
Asperger's syndrome (1 paper, 2025). "A nonsense variant in CLN8 in the heterozygous state segregated with ASD in a Japanese family consisting of a father diagnosed with PDD-NOS and three sons diagnosed with Asperger's syndrome." (PMID 40988857, 2025).
autosomal recessive retinitis pigmentosa (1 paper, 2024). Autosomal recessive retinitis pigmentosa (RP) is an autosomally recessive inherited retinal dystrophy leading to progressive loss of the photoreceptors and retinal pigment epithelium and resulting in blindness usually after several decades. "Patient four had a clinical diagnosis of retinitis pigmentosa and Invitae reported this patient to have a pathogenic mutation in CLN8, which is associated with autosomal recessive retinitis pigmentosa; however, CLN8 is not included in the BG panel." (PMID 38892829, 2024).
cognitive decline (1 paper, 2025). "CLN8 and other neuronal ceroid lipofuscinoses (NCLs) often lead to cognitive decline, emotional disturbances, and social deficits, worsening with disease progression." (PMID 39791756, 2025).
ear tumors (1 paper, 2021). "We found that there was a significant (P<0.05) differential expression (≥ 1.4 or ≤ -1.4-fold, RPKM ≥ 0.5) of 8 genes in the ear tumors, of which one (Cln8) had a viral DNA integrated in a 6-kb terminal exon and was upregulated." (PMID 34343212, 2021).
Epileptic seizures (1 paper, 2005). "Epileptic seizures are a characteristic feature in human patients with CLN8 mutations." (PMID 15826318, 2005). "We therefore analyzed, by mRNA in situ hybridization analysis, possible changes in Cln8 expression 2 h, 6 h and 24 h after kindling-induced epileptic seizures." (PMID 15826318, 2005).
Kufs disease (1 paper, 2021). "CLN6 and CLN8 proteins, deficient in CLN6 (also known as Kufs disease) and CLN8 disorders, respectively, form a complex (termed EGRESS: ER-to-Golgi relaying of enzymes of the lysosomal system), which recruits lysosomal enzymes in the ER to facilitate their transfer to Golgi via COPII vesicles." (PMID 33996898, 2021).
neurodegenerative disease (4 papers, 2010 to 2025). A disorder of the central nervous system characterized by gradual and progressive loss of neural tissue and neurologic function. "A recent characterization of CLN8, a gene involved in human progressive epilepsy and found on CFA 37, was found to be mutated in English Setter dogs having heritable neurodegenerative disease." (PMID 20441595, 2010). "Furthermore, mutations in CLN8 have been linked to neuronal ceroid lipofuscinoses (NCL), a prevalent neurodegenerative disease in childhood." (PMID 40170191, 2025).
cancer (3 papers, 2008 to 2023). A tumor composed of atypical neoplastic, often pleomorphic cells that invade other tissues. "However, more research is needed in the future to explore the importance of CLN8 in cancers." (PMID 37489460, 2023). "A literature survey about significant biomarkers highlighted in survival analysis revealed that GNG11, CBX2, CDKN3, ARHGEF10, CLN8, SEC61G and PTDSS1 genes present similar survival and prognostic behaviors in the specified cancers." (PMID 37489460, 2023). "Expression data for multiple cancer cell lines (not shown) suggested ARHGEF10 as a more likely target gene than CLN8, since ARHGEF10 expression was decreased by more than 50% in 83% (15/18) of lines tested." (PMID 18840272, 2008).
infection (1 paper, 2016). The state of being infected such as from the introduction of a foreign agent such as serum, vaccine, antigenic substance or organism. "In contrast, ADAMTS18, CLN8, RDH10 and TNPO1 were shown to be up-regulated following infection in HSaVEC, indicating that gene regulation differs for these genes between the endothelial cells." (PMID 26837541, 2016).
CLN8 also shares sentences with these, for which no sentence is quoted: tumor (4 papers); autism spectrum disorder (2); neurological diseases (2); neuronal ceroid lipofuscinosis 8 (2); Ataxia (1); brain cancer (1); childhood asthma (1); colorectal cancer (1); dementia (1); glioma (1); Kaya-Barakat-Masson syndrome (1); lysosomal storage disorder (1); Macular dystrophy (1); Onset (1); preeclampsia (1); retinal degeneration (1); retinitis pigmentosa (1); sphingolipidoses (1); Tremor (1); Wolman disease (1).